MMP8 (matrix metallopeptidase 8)
Diseases named in the same sentence as MMP8 in open-access papers (continued):
Sharing a sentence is not in itself a finding about the gene and the disease.
Sepsis (62 papers, 2010 to 2026). Sepsis is defined as life-threatening organ dysfunction caused by a dysregulated host response to infection. "Genetic downregulation and pharmacologic inhibition of MMP8 have been associated with neuroprotection in a murine sepsis model, where animals with elevated levels of the protein had increased central nervous system inflammation and toxicity." (PMID 40383794, 2025). "In the present study, we found that MMP8 acts as a key gene in the progression of sepsis and is associated with an unfavorable prognosis in patients with sepsis." (PMID 35145983, 2022). "Leukocyte adhesion to vascular and matrix Metalloproteinase-8 (MMP8) expression is increased in sepsis and associated with poor prognosis in sepsis patients." (PMID 35145983, 2022). "MMP8 rs11225395 G/G carriers have lower temperature at presentation and a more than 50% increased susceptibility to sepsis." (PMID 35204780, 2022). "The most upregulated gene in the “neutrophil activation” term in sepsis was MMP8, which encodes a member of the MMP family of proteolytic enzymes that play multiple roles in the immune response to infection." (PMID 36443881, 2022). "Matrix Metallopeptidase 8 and Olfactomedin 4 have been associated with sepsis-induced respiratory distress." (PMID 34200950, 2021). "The genes overexpressed in ARDS were often found to be associated with a more severe sepsis outcome in other studies (including MMP8, RETN, and OLFM4)." (PMID 33692779, 2021). "In patients with sepsis, high levels of MMP-8 have been associated with increased ICU and 28-day mortality, whereas lower levels of MMP-9 have been linked to better survival." (PMID 25945788, 2015). "Sepsis associated with increased MMP-8 and decreased MMP-9 levels in multivariate analysis (p < 0.0002)." (PMID 24833564, 2014). "Peripheral blood transcriptomics in humans have shown a parallel scenario since particular key mediators of the initial neutrophil response to infection, such as LCN2, BPI, CD24, CASP1 and MMP8, were strongly dysregulated in patients with sepsis-associated ARDS compared to sepsis patients." (PMID 31426444, 2019). "In sepsis, altered levels of MMP-8, MMP-9, and TIMP-1 have been associated with adverse outcome." (PMID 25945788, 2015). "This study aimed to analyze the effects of glutamine and arginine combination (GAC) on TNF-α, NF-κB, IL-8, and MMP-8 expressions in sepsis." (PMID 42294010, 2026). "Using RT-qPCR, we confirmed the upregulation of HP, C3, Chil3/CHI3L1, and MMP8 in renal microvascular compartments in both CLP-sepsis mice and human post-mortem kidney biopsies from patients with SA-AKI." (PMID 40892345, 2025). "In our prior work, we observed neutrophil infiltration in the glomerular compartment during sepsis, and MMP8 is a well-established product of immune cells in inflammatory contexts." (PMID 40892345, 2025). "The PERiPLEX® system utilizes a lateral flow assay to MMP-8 and IL-6, utilizing peritoneal dialysate derived from a dialysis effluent as significant inflammatory indicators with high concentrations during sepsis cases." (PMID 38893639, 2024). "In animal models of sepsis, MMP-8 cleaves collagen in the extracellular matrix of the choroid plexus, increasing barrier permeability." (PMID 36445634, 2023). "Using the rms package, we developed nomogram models for diagnosing pediatric sepsis based on the hallmark genes CYSTMI1, MMP8, and CD177." (PMID 37115484, 2023). "S100A8, MMP8, CSF3 and IL-6 protein levels in the peripheral blood of sepsis patients were revealed to be substantially associated with GCS scores following a correlation investigation of the four extracellular molecules with clinical indications (all p<0.05)." (PMID 37901226, 2023). "In healthy individuals, plasma MMP8 protein levels are modest; nevertheless, in sepsis, particularly in those who have had a combined brain injury, plasma MMP8 levels are considerably raised and are correlated with the degree of distant brain function." (PMID 37901226, 2023).
Sepsis (continued). "The diagnostic and prognostic accuracy of MMP8 and S100A8 was evaluated using clinical peripheral blood samples, CSF, and behavioral experiments in a rat model of sepsis." (PMID 37901226, 2023). "The candidate hub genes (CD177, CYSTM1, and MMP8) were identified, and the nomogram was constructed for pediatric sepsis diagnosis." (PMID 37115484, 2023). "As pediatric sepsis diagnostic indicators, CYSTM1 (AUC = 0.988), MMP8 (AUC = 0.973), and CD177 (AUC = 0.986) were investigated and demonstrated statistically significant differences (P < 0.05) and diagnostic efficacy in the validation set." (PMID 37115484, 2023). "We subsequently assessed the level of MMP-8 expression in various disease gene sets and found a significant increase in its expression level among the sepsis, severe asthma, and pneumonia groups as compared to healthy individuals." (PMID 37464428, 2023). "In comparison to the sham-operated group, sepsis rats had higher levels of MMP8 and S100A8 proteins in their venous blood (both p<0.05) and cerebrospinal fluid (p=0.0506, p<0.0001, respectively)." (PMID 37901226, 2023). "Other studies have identified other MMP variants as associated with sepsis susceptibility or prognosis: MMP-1, MMP-3, MMP-8, and TIMP-1 variants have already been investigated in sepsis outcome in a few hundred ICU patients with severe sepsis." (PMID 35204780, 2022). "In fact, the eventual mortality of patients has been associated with the elevated levels of MMP‐2, MMP‐9, MMP‐8, and TIMP‐1, as observed in the early stages of sepsis." (PMID 35818743, 2022). "MMP-8 is upregulated in sepsis, although laboratory models and molecular biology only show that its presence ensures neutrophil infiltration in response to lipopolysaccharide, likely through the degradation of LIX CXC chemokines." (PMID 35204780, 2022). "The mRNA and protein expression of MMP8 in blood from sepsis patients were significantly higher than controls." (PMID 35145983, 2022). "MMP8 plays a crucial role in the prognosis of sepsis patients based on the results of an in silico study, and MMP8 can promote the expression of VCAM-1 in patients with atherosclerosis." (PMID 35145983, 2022). "Bioinformatics analysis of GSE64457 and GSE65682 was performed to evaluate the role of MMP8 in the progression of sepsis." (PMID 35145983, 2022). "Only three genes (EGR1, MMP8, and cd44) were shown to be prevalent in the DEGs of sepsis, SLE, and CRS." (PMID 35205254, 2022). "Previous evidence that MMP-8 plays a role in sepsis is heterogeneous: in the cecal ligation perforation procedure, MMP-8 inhibition increases survival and high plasma values predict sepsis compared with other patients admitted to ICU." (PMID 35204780, 2022). "This study sheds light on the role of MMP8 in the development of sepsis and provides a potential therapeutic target for sepsis." (PMID 35145983, 2022). "Gene expression (2.360 ± 0.966 vs. 22.900 ± 6.845, p < 0.05) and protein expression (647.6 ± 69.37 vs. 1081 ± 119.3, p < 0.05) of MMP8 was significantly higher in sepsis patients than in healthy controls." (PMID 35145983, 2022). "Human umbilical vein endothelial cells (HUVECs) were treated with sepsis serum, control serum, and MMP8 inhibitor." (PMID 35145983, 2022). "The gene and protein expression of MMP8 were validated by qRT-PCR and ELISA in six sepsis patients and five healthy controls." (PMID 35145983, 2022). "Concerning the transcripts related to “neutrophil activation,” matrix metalloproteinase 8 (MMP8) showed the highest upregulation in sepsis samples, followed by olfactomedin 4 (OLFM4) and resistin (RETN)." (PMID 36443881, 2022). "High Pitt bacteremia score, severe sepsis and ICU treatment were associated to higher MMP-8 concentrations at day 3 and day 5 (p<0.01) and higher TIMP-1 at day 3 (p<0.05) whereas no connection to day TIMP-1 was observed." (PMID 34043679, 2021). "Patients with severe sepsis or infection focus presented higher MMP-8 levels at day 3 and 5 (p<0.01)." (PMID 34043679, 2021).
Sepsis (continued). "In this study, we aimed to evaluate the diagnostic value of several MMPs (MMP-2, MMP-9, MMP-8) and TIMPs (TIMP-1 and TIMP-2) for equine colic, which is often associated with endotoxemia and sepsis in case of strangulating obstruction." (PMID 33488296, 2021). "Gene ablation studies have indicated that MMP-8 facilitates sepsis in animal models, while MT1-MMP is protective." (PMID 31795279, 2019). "MMP-9, TIMP-2 and TIMP-1 have been shown to be elevated in patients with severe sepsis and septic shock as well as in animal models of endotoxemia, while MMP-1, MMP-8 and MMP-13 have also been associated with sepsis." (PMID 30466423, 2018). "In the context of sepsis, our group developed a bispecific Nb that targets MMP8 and TNFR1, as discussed in Section 3.2.2." (PMID 29751683, 2018). "MMP-8 was upregulated in LPS-stimulated microglia and in the brains of mice with sepsis, and treatment with an MMP-8 inhibitor (M8I) dramatically suppressed the secretion of proinflammatory molecules, particularly TNF-α." (PMID 29108257, 2017). "Because of the sepsis- induced considerable rise in MMP-8 concentration we assessed the presence of sepsis at study admission without positive findings." (PMID 27561093, 2016). "The levels of MMP-8 in patients in our study were lower compared with those found in sepsis patients." (PMID 27561093, 2016). "In severe sepsis and septic shock, MMP-8 released from neutrophil granulocytes has been reported to associate with an unfavourable outcome." (PMID 27561093, 2016). "In a study of patients with severe sepsis, suction blister fluids from severely septic patients contained similar levels of MMP-8 as burn blister fluids in our study." (PMID 25945788, 2015). "In retrospective studies on sepsis, levels of MMP-8, MMP-9, and tissue inhibitor of metalloproteinase-1 (TIMP-1) differed from those of healthy controls, and TIMP-1 showed an association with outcome." (PMID 25945788, 2015). "In that study, the blister fluid in the early stage of sepsis had higher MMP-8 and lower MMP-9 than in controls." (PMID 25945788, 2015). "High MMP-8 and low MMP-9, which correlated with plasma CRP levels, were associated with sepsis, in addition to high fibrinogen levels and neutrophils counts." (PMID 24833564, 2014). "In conclusion, we report for the first time an association between the MMP-13 and the MMP-1 SNPs and sepsis, as well as an independent association of plasma MMP-8 and MMP-9 levels with sepsis." (PMID 24833564, 2014). "The area under the ROC curve for MMP-8 in the diagnosis of sepsis was 0.87 (95% CI 0.82–0.92), p < 0.0001." (PMID 24833564, 2014). "The area under the ROC curve for MMP-8 in the diagnosis of sepsis was 0.87 (95% CI 0.82–0.92), and that of CRP was 0.98 (0.94–0.998), whereas the area of MMP-9 in the detection of non-septic state was 0.73 (0.65–0.80), p < 0.0001 for all curves." (PMID 24833564, 2014). "Regarding to MMP-8 and sepsis, all the experimental models using LPS, either intratracheal or intraperitoneal (present study), report an increase in lung inflammation in knockout mice." (PMID 22768176, 2012). "This anti-inflammatory role of MMP-8 must be considered before proposing anti-MMP strategies in sepsis." (PMID 22768176, 2012). "In conclusion, the results described here reinforce the central role of MMP-8 in the regulation of neutrophil recruitment to the lungs during sepsis, adding the myeloid-related proteins S100A8 and S100A9 as one of the involved mediators." (PMID 22768176, 2012). "The MMP-8 levels in blister fluid samples were significantly higher in patients with severe sepsis in comparison with the controls on both days." (PMID 20356362, 2010). "Upregulation of HP, C3, Chil3/CHI3L1, and MMP8 in renal microvascular compartments of both mice and humans may reflect endothelial activation in sepsis, as supported by prior transcriptomic and proteomic studies." (PMID 40892345, 2025).
Sepsis (continued). "Mmp8 and Chil3 showed clear upregulation in both the kidney and liver following sepsis." (PMID 40892345, 2025). "It is evident that MMP8 functions as a new regulator of inflammation in sepsis." (PMID 37115484, 2023). "This study concluded that CYSTM1, MMP8 and CD177 are pediatric sepsis diagnostic indicators." (PMID 37115484, 2023). "This suggests that MMP8 may function as a biological marker of brain impairment brought on by sepsis." (PMID 37901226, 2023). "Our study indicated that MMP8 acts as a key gene in the development of sepsis, and sepsis serum promotes leukocyte adhesion to HUVECs via MMP8, which suggest that MMP8 might be a potential therapeutic target for sepsis." (PMID 35145983, 2022). "Consequently, it can also be extrapolated that infections/sepsis by pathogens occur at a higher than expected rate and local MMP8-mediated inflammation prevents spreading of the germ and pathogenicity." (PMID 35204780, 2022). "In investigating the role of MMP-8 rs11225395 in sepsis, only one study has evaluated this variant, with negative results." (PMID 35204780, 2022). "However, our result revealed increased expression of MMP8 in sepsis than in COVID-19 samples, indicating that MMP8 expression was highly upregulated by bacteria in sepsis samples." (PMID 36443881, 2022). "It is clear that MMP8 works as a novel inflammatory modulator in sepsis." (PMID 35145983, 2022). "Interestingly, gene expression and protein expression of MMP8 were significantly higher in patients with severe sepsis than in healthy controls." (PMID 35145983, 2022). "Expression of MMP8 in blood samples from patients with sepsis was detected by qRT-PCR and ELISA." (PMID 35145983, 2022). "Therefore, excessive leukocyte adhesion to endothelial vascular stimulation by MMP8 is detrimental to the survival of sepsis patients." (PMID 35145983, 2022). "However, the MMP8 inhibitor suppressed the leukocyte adhesion promoted by sepsis serum by decreasing the expression of VCAM-1, ICAM-1, p-p38, and p-ERK1/2." (PMID 35145983, 2022). "MMP8 was selected as a key gene with an unfavorable prognosis in sepsis patients." (PMID 35145983, 2022). "This study aimed to investigate the role of MMP8 in sepsis serum mediated leukocyte adhesion." (PMID 35145983, 2022). "GPs of MMPs and TIMP (namely MMP-1 rs1799750, MMP-3 rs3025058, MMP-8 rs11225395, MMP-9 rs2234681, and TIMP-1 rs4898) have been compared in 1058 patients with suspected sepsis to assess the association with susceptibility and etiology of sepsis." (PMID 35204780, 2022). "Matrix Metallopeptidase 8 has been identified as a marker to distinguish sepsis and estimate the probability of mortality in septic shock, as well as a novel modulator of inflammation during sepsis and a potential therapeutic target in this disease." (PMID 34200950, 2021). "Only two of these biomarkers seemed relevant to differentiate sepsis from plain infection (lipocalin 2 and MMP8), suggesting that neutrophil degranulation may be important in the pathogenesis of septic shock." (PMID 32073224, 2020). "A survival advantage during sepsis was observed for Mmp8 null mice compared with wild-type mice." (PMID 31795279, 2019). "High levels of MMP-8 have been correlated with fatal outcomes in sepsis." (PMID 31461880, 2019). "Indeed, former research of the lab reported an important interplay between TNFR1 signaling and MMP8 in sepsis." (PMID 29751683, 2018). "Moreover, compstatin counteracted the effects of E. coli sepsis on the expression of matrix metalloproteinases MMP8, MMP9 and MMP14." (PMID 26337158, 2015). "An independent association of MMP-8 and MMP-9 levels with sepsis was also observed." (PMID 24833564, 2014). "In human sepsis, MMP-8 correlates with severity, mortality and organ failures." (PMID 22768176, 2012).
Sepsis (continued). "The main findings were the levels of MMP-2 and MMP-8 were up-regulated in severe sepsis both in skin blister fluid and in the serum, MMP-2 levels were higher in skin blister fluid as well as in serum in more severe organ failures, and at three and six months the MMP levels had returned to normal." (PMID 20356362, 2010). "Therefore, HP, C3, Chil3/CHI3L1, and MMP8 have established roles in immune modulation, inflammation, and the oxidative stress response, and our study demonstrates their upregulation as part of the endothelial activation signature in sepsis." (PMID 40892345, 2025). "Furthermore, only one patient (MMP8) developed a severe infection, specifically sepsis." (PMID 37143653, 2023). "Therefore, we hypothesized that MMP8 plays a vital role in leukocyte adhesion to endothelial cells in patients with sepsis." (PMID 35145983, 2022). "Additionally, MMP8 expression is upregulated in sepsis and COVID-19 samples." (PMID 36443881, 2022). "Moreover, we combined significant clinical indicators (direct lung injury, shock and tumor) and genetic biomarkers (BPI, MME and MMP8) to generate a predictive model of ARDS in patients with sepsis, which showed good performance in terms of discriminatory capacity and goodness of fit." (PMID 36685531, 2022). "Interestingly, MMP8 gene expression is overexpressed in children with septic shock, and the serum MMP8 levels have been reported to be significantly higher in patients with severe sepsis than in healthy controls." (PMID 35145983, 2022). "The present study reports the associations between MMP-8 rs11225395 G/G genotype and sepsis compared to patients without sepsis and, moreover, of the MMP-1 rs1799750 and MMP-3 rs3025058 genotypes with diagnosis of sepsis due to intracellular pathogens or virus, respectively." (PMID 35204780, 2022). "Therefore, we hypothesized that MMP8 is an important inflammatory mediator that mediates sepsis serum-promoted leukocyte adhesion to HUVECs." (PMID 35145983, 2022). "Activation of the NF-κB signaling pathway in sepsis plays a crucial role in the expression of TNF-α, IL-8, and MMP-8, which can further exacerbate the condition." (PMID 42294010, 2026). "In the ICU cohort, which represented more advanced sepsis, levels of CHI3L1 (median 392 vs. 985 ng/mL, P < 0.01) and MMP8 (median 23 vs. 98 ng/mL, P = 0.05) were significantly higher in patients with SA-AKI compared to those with sepsis." (PMID 40892345, 2025). "Circulating protein levels were elevated in sepsis and SA-AKI patients compared to controls; however, only CHI3L1 and MMP8 showed significantly higher levels in SA-AKI versus sepsis across both early and advanced stages." (PMID 40892345, 2025). "The CoIP results confirmed direct interactions between MMP8, MMP9, ARG1, and CXCL8, substantiating their roles in sepsis-related inflammatory pathways." (PMID 39560539, 2024). "Our study underscores the significant potential of biomarkers such as MMP8, MMP9, and ARG1 in advancing the early diagnosis and targeted treatment of sepsis." (PMID 39560539, 2024). "This study’s bioinformatics analysis has identified significant alterations in the expression of genes such as MMP8, MMP9, and ARG1 in the granulocytes of patients with sepsis." (PMID 39560539, 2024). "In agreement, another study reported an inverse relationship between the plasma levels of IL-6, MMP-8 and CXCL9 (indicative of systemic inflammation) and the TNF production capacity of whole blood obtained from patients with sepsis." (PMID 37415223, 2023). "In the GSE13904 validation set, the expression of CYSTM1, MMP8, and CD177 was considerably higher in the pediatric sepsis group than in the control group (P < 0.01)." (PMID 37115484, 2023). "Numerous reports have indicated a definite link between the two hub genes, MMP8 and CD177, and the process of sepsis to some extent." (PMID 37115484, 2023).